MYC (MYC proto-oncogene, bHLH transcription factor)
Diseases named in the same sentence as MYC in open-access papers (continued):
Sharing a sentence is not in itself a finding about the gene and the disease.
Burkitt lymphoma (continued). "Here, we take advantage of MYC-, IL6- and IL6MYC-transgenic (Tg) mice that recapitulate important features of human Burkitt lymphoma (BL) or multiple myeloma (MM) to uncover up-regulated candidate cancer genes that might have been overlooked in other studies." (PMID 25838973, 2015). "Translocation and deregulation involving MYC gene on chromosome 8 is highly characteristic but not specific for Burkitt’s lymphoma." (PMID 25364378, 2014). "That MYC transcription in GLC4 is reported to initiate mainly from P1 instead of the P2 promoter and that this promoter shift seems to overcome transcript termination at a transcriptional pause site described for Burkitt’s lymphoma." (PMID 24466310, 2014). "Regimens [CODOX-M/IVAC] thought to be active in Burkitt lymphoma (MYC translocation) did not confirm effectiveness." (PMID 24893165, 2014). "For example, the upstream promoter of MYC, dominant negative in normal tissue, is aberrantly activated in Burkitt's lymphoma cells due to aberrant translocation of MYC gene locus." (PMID 20208995, 2010). "In Burkitt lymphoma (BL), KLF4 acts as a tumor suppressor by reducing MYC expression and its downstream target EZH2 while activating tumor suppressors such as TXNIP." (PMID 39995670, 2025). "Furthermore, expression levels of EZH2 and c-MYC in liver tissue were reduced in the dEZH2-treated group compared to control, suggesting that dEZH2 maintains EZH2 degradation activity in vivo and effectively inhibits the progression of Burkitt’s lymphoma." (PMID 40308579, 2025). "However, beyond Burkitt lymphoma, it is unknown whether these observations extend to other cancers or MYC family members, and whether WDR5 can be deemed as a “universal” MYC recruiter." (PMID 37336886, 2023). "To investigate whether MYCMI-7 affects growth of typical MYC-driven tumor cells, we utilized a panel of childhood neuroblastoma cells with or without MYCN-amplification as well as a set of Burkitt's lymphoma cell lines, which carry MYC translocations." (PMID 36874405, 2022). "While studying c-Myc protein expression in several Burkitt lymphoma cell lines and in lymph nodes from a mouse model bearing a translocated c-MYC gene from the human BL line IARC-BL60, we surprisingly discovered a complex electrophoretic profile." (PMID 35740961, 2022). "The occurrence of MYC-negative Burkitt lymphoma (BL) has been discussed for many years." (PMID 35167621, 2022). "Importantly, this observation has been seen in human Burkitt’s lymphoma where BIM expression is virtually absent in tumours carrying mutant MYC." (PMID 33799592, 2021). "Of great interest, MYC-translocated Burkitt lymphomas showed more sensitive to CS2164 treatment than DLBCL and mantel cell lymphomas, prompting us to investigate the effect of CS2164 alone or in combination with the BCL2 inhibitor venetoclax on the MYC-translocated HGBL-DHL." (PMID 33777762, 2021). "Human and mouse tumour cells driven by deregulated over-expression of c-MYC are highly dependent on the anti-apoptotic protein MCL-1 for survival and the MCL-1-specific BH3 mimetic drug S63845 induces dose dependent apoptotic death in murine Eμ-Myc as well as human Burkitt’s lymphoma cell lines." (PMID 32555451, 2020). "The existence of BL tumours negative for EBER-1 and MYC Burkitt's lymphoma may be suggestive of alternative pathogenesis mechanisms or a variant(s) and needs further studies." (PMID 32180880, 2019). "Importantly, the absence of a MYC translocation does not rule out a diagnosis of Burkitt's lymphoma; in up to 10% of cases, fluorescence in situ hybridization is negative for these translocations." (PMID 29593916, 2018).
Burkitt lymphoma (continued). "However, Burkitt lymphoma cases with no detectable MYC rearrangement but maintaining MYC expression have been identified and alternative mechanisms can be involved in MYC dysregulation in these cases." (PMID 26453442, 2015). "MYC-IGK translocations are not uncommon in Burkitt lymphoma, occurring with a 5-10% frequency." (PMID 23957733, 2013). "Two independent laboratories have reported that a subset of DLBCLs have a gene transcriptional profile resembling Burkitt lymphoma (“molecular Burkitt lymphoma”, mBL), and that these cases largely, but not completely, overlap with those tumors harboring a MYC translocation." (PMID 22511926, 2012). "Finally, when 173 human mature aggressive B lymphoma samples were used for the clustering of the 51 gene MCS, molecular Burkitt's lymphoma (mBL) cases have distinctly higher MYC and MCS expression than the non-mBLcases." (PMID 22039435, 2011). "IG::MYC: Although IG::MYC translocations are typical of Burkitt lymphoma (BL), WHO-HAEM5 reports infrequent cases of BL with a phenotype of precursor B-cells including expression of terminal deoxynucleotidyl transferase, sometimes CD34, and absence of CD20 and surface immunoglobulin expression." (PMID 38835965, 2024). "In a study of Burkitt lymphoma, it was demonstrated that the use of LDH-specific inhibitors could result in a reduction in MYC protein levels through NAD/NADH-dependent inhibition of sirtuin-1, thereby depriving BL cells of the most important survival signal." (PMID 39464313, 2024). "The MYC gene has been often found to be close to the IGH gene locus compared with the IGL and IGK gene loci, which may explain why the MYC-IGH translocation is observed in around 80% of Burkitt’s lymphoma cases while the remaining MYC-IGK and MYC-IGL translocations occupy the rest." (PMID 36291894, 2022). "Indeed, another study has put into question whether the regulatory link between MINCR and MYC is universal, since it was not reproducible using data generated from an independent set of Burkitt lymphoma cells." (PMID 33134177, 2020). "However, MYC is not the only HSP90 client protein in Burkitt lymphoma, and so it is possible that the mechanism of action is not exclusively through MYC, but involves the destabilization of cell cycle regulators such as CDK2 and CDK4 directly due to loss of HSP90 function." (PMID 30453475, 2018). "However, additional DLBCLs that may not harbor a MYC translocation exhibit features of “molecular Burkitt lymphoma (mBL)” by gene expression profiling (GEP)." (PMID 22511926, 2012). "Burkitt lymphoma (BL) is a B-cell tumor that arises as a consequence of chromosomal translocations that juxtapose the c-MYC proto-oncogene to Ig-gene enhancers, resulting in constitutive over-expression of c-MYC." (PMID 19551150, 2009). "FISH revealed MYC rearrangement, but the partner gene was not IGH, the typical fusion seen in Burkitt lymphoma." (PMID 41374977, 2025). "Additionally, CD97 was identified as a possible MYC-target gene specifically expressed in Burkitt lymphoma (BL), but not in diffuse large B-cell lymphoma (DLBCL)." (PMID 36982575, 2023). "We studied the classical MYC driven malignancy Burkitt lymphoma, as well as diffuse large B-cell lymphoma (DLBCL) with and without MYC translocation." (PMID 36792656, 2023). "The definition of Burkitt lymphoma (BL) in WHO-HAEM5 remains largely unchanged, describing BL as an aggressive mature B-cell neoplasm composed of medium-sized cells with a germinal center B-cell phenotype CD10+, BCL6+, BCL2-/weak, high Ki67 index (>95%) and an IG::MYC juxtaposition." (PMID 35732829, 2022). "Another group treating Burkitt lymphoma cells with the HSP90 inhibitor, PU176, also reported reduced tumor cell proliferation; however, they suggested the PI3K/AKT/mTOR pathway (but not MYC) as the main mechanism of action." (PMID 30453475, 2018). "For a long time it was a matter of debate whether true Burkitt lymphoma (BL) without MYC translocation does exist." (PMID 29250206, 2017).
Burkitt lymphoma (continued). "To this end we performed proliferation assays with apoptosis-resistant BCL2 overexpressing MYC-transgenic mouse B cells, pre-B ALL cells lacking BAX/BAK, as well as BCL2 overexpressing Burkitt lymphoma cell lines." (PMID 29167438, 2017). "To investigate the role of DNMTs in MYC-driven tumor maintenance, we performed expression profiling on T-ALL and Burkitt’s lymphoma compared to non-malignant tissue." (PMID 29100357, 2017). "To unravel the role of DNA methyltransferases (DNMTs) in MYC-driven hematopoietic malignancies, we performed expression profiling for DNMT1, DNMT3A and DNMT3B comparing MYC-driven T-ALL and Burkitt’s lymphoma cells to non-malignant control cells." (PMID 29100357, 2017). "MYC rearrangements in DLBCL can be partnered with IGH but, compared with Burkitt lymphoma, are more frequently partnered with the IGL or to non-IG genes such as BCL6, BCL11A, PAX5 or ICAROS49." (PMID 26416427, 2015). "Furthermore, c-MYC rearrangement is not unique in Burkitt’s lymphoma and may occur in DLBCLs." (PMID 25364378, 2014). "c-MYC protein expression has been suggested to favour Burkitt’s lymphoma over DLBCL, but rare cases of Burkitt’s lymphoma can be c-MYC protein negative and some large B-cell lymphomas also express c-MYC protein (5%–15% of them having a MYC rearrangement)." (PMID 25364378, 2014). "The expression of CD58 is markedly elevated in Burkitt’s Lymphoma (BL) compared to BCP-ALL, and it can be used to aid in the diagnosis when BL is suspected but MYC proto-oncogene (C-MYC) rearrangement is negative and the results of surface Ig assessment are controversial." (PMID 40365344, 2025). "An exon-specific RT-qPCR assay using two pairs of Burkitt’s lymphoma cell lines (CA46 and RAJI), devised by Brooks group, allowed us to evaluate whether G4 ligands directly act for c-MYC G4 or not in cells." (PMID 30682877, 2019).
leukemia (538 papers, 2007 to 2026). A malignant (clonal) hematologic disorder, involving hematopoietic stem cells and characterized by the presence of primitive or atypical myeloid or lymphoid cells in the bone marrow and the blood. "c‐MYC (hereafter MYC) was first identified as the cellular homolog of v‐Myc, the retroviral oncogene causing myelocytosis and leukemia." (PMID 40488968, 2025). "Although aberrant expression of MYC is observed in many solid tumors as well as leukemia, MYCN is more commonly associated with neuroblastoma and other neuroendocrine tumors and MYCL is predominantly deregulated in small‐cell lung cancer." (PMID 40488968, 2025). "We took advantage of the MYC-GFP reporter to enumerate the specific impact of CHMP5 deficiency on leukemia-initiating cells (LIC) wherein LICs in ICN1-driven T-ALL express CD34 and MYC13,66." (PMID 40319015, 2025). "In a leukemia model, it led to the degradation of MYC and epigenetic reprogramming, including a significant loss of lysine acetylation in histone H3 and the downregulation of histone acetyltransferases." (PMID 38132962, 2023). "c-MYC protein is linked to drug resistance in leukaemia cells and found to be involved in the microenvironment-mediated drug resistance." (PMID 37098530, 2023). "c-MYC was discovered almost 40 years ago as the cellular homolog of v-Myc, a viral oncogene derived from an avian myelocytomatosis virus that caused leukaemia and sarcoma in chicken." (PMID 35267559, 2022). "GSEA results revealed that genes involved in “E2F_targets”, “G2M_checkpoint”, and “MYC_targets” were increased and enriched in Rora deficient leukemia cells." (PMID 35414788, 2022). "Subsequent c-MYC downregulation was probably linked to anti-leukaemia activities, including cell-cycle arrest and glycolysis inhibition, along with ribosome biogenesis repression, which diminished AML1-ETO protein synthesis." (PMID 33833412, 2022). "Overexpression of MYC is associated with poor prognosis of various malignant diseases including leukemia." (PMID 34564151, 2021). "Worthy to note, the H3K27ac peaks within the well-established BENC super enhancer (E1-E5 associated with MYC expression) were all attenuated in leukemia cell lines with high IC50 values for BETi (red traces)." (PMID 32029739, 2020). "By using dCas9-KRAB based epigenome editing method to modulate H3K27ac levels with high precision, we have established the causal relations between this particular enhancer and MYC expression in BETi-treated leukemia cells." (PMID 32029739, 2020). "In fact, the Eμ-myc murine leukemia model has demonstrated that the deletion of Bim counteracts the potential induction of cell death by MYC, worsening the B-cell leukemia-associated prognosis of these mice." (PMID 32102485, 2020). "Among these shared pathways, 76% (543 out of 717) overlapped in MOLM13 compared with K562 cells treated with Ro, which included c-MYC, mRNA-related, and leukemia-associated gene sets." (PMID 31217428, 2019). "YTHDF2, responsible for the decay of m6A-modified mRNA transcripts, is also associated with MYC in leukemia." (PMID 31142332, 2019). "N-Me-mediated MYC upregulation was even more significant in leukemia initiation, where the loss of one and two copies of N-Me delayed and completely abrogated tumor development." (PMID 31311566, 2019). "Here, we demonstrate that cardiac glycoside proscillaridin A specifically targets MYC overexpressing leukemia cells and leukemia stem cells by causing MYC degradation, epigenetic reprogramming and leukemia differentiation through loss of lysine acetylation." (PMID 31196146, 2019). "Intriguingly, while SIRT1 was shown to regulate c-MYC in Flt3-ITD mutated leukemia, it has been demonstrated to regulate Mxd1 in malignant melanoma." (PMID 30420889, 2018). "All these results were comparable to those of U937 cells, suggesting that AKT, ERK1/2, SAPK/JNK/MAPK signaling cascades involved c-MYC inhibition play a general role in shikonin-caused leukemia cell death." (PMID 26472107, 2015).
leukemia (continued). "MYC activity has been mainly associated with aggressive, high grade B-cell malignancies, and mice with overexpression of Myc in B cells (Eμ-Myc) develop an aggressive lymphoma/leukemia." (PMID 34417556, 2022). "Therefore, we tested for a potential impact of RGFP966 on the leukemia- and stemness-associated transcription factors β-catenin, MYC, and WT1." (PMID 31561534, 2019). "Proscillaridin A induced a rapid loss of MYC protein expression in MYC-driven leukemia cells through the downregulation of series of KATs (KAT2A, KAT3A, KAT3B, KAT5 and KAT6A) known to be involved in MYC protein stability (by lysine acetylation) and activation of MYC transcriptional programs." (PMID 31196146, 2019). "The use of R-2HG and MYC inhibitors could enhance cytotoxicity, which indicates that the combined utilization of R-2HG and MYC may be an effective treatment method for patients with leukemia characterized by an IDH mutation." (PMID 31757221, 2019). "Therefore, proscillaridin A targets MYC overexpressing leukemia cells by reducing MYC protein half-life, causing its rapid degradation." (PMID 31196146, 2019). "The genetic profile of this cell line and leukemia cases containing t(8:14)(q24;q11) leading to MYC overexpression with NOTCH1wt/FBXW7wt/PTEN mutation or deletion resembles that of a recently described Notch1-independent mouse leukemia model arising following conditional Pten deletion." (PMID 30304769, 2018). "We found the novel LEF1 mutations could promote the cell proliferation of leukemia cells by regulation of gene expression of LEF1 targets: c-MYC and Cyclin D1." (PMID 25942645, 2015). "Moreover, Following HMGCR inhibition with pitavastatin treatment, an attenuated oncogenic AKT1 signaling was evident along with the suppression of MYC signaling pathway expression via the loss of chromatin accessibility at the leukemia stem cell-specific long-range MYC enhancer." (PMID 37745085, 2023). "Specifically, R-2HG inhibited FTO activity, thereby increasing global m6A RNA modification and reducing the stability of MYC/CEBPA transcripts in R-2HG-sensitive leukemia cells, showing antitumor activity." (PMID 41362736, 2026). "Individual markers, particularly JUP, MYC, and NT5C3B, showed good diagnostic accuracy for distinguishing leukemia from non-leukemia." (PMID 41596324, 2026). "Functionally, UBE2D3 acts as a critical downstream effector that sustains leukemia cell proliferation and survival through MYC-dependent signaling." (PMID 41926643, 2026). "c-MYC is a well-known oncogene and is one of the most commonly activated in human cancers, including leukemia." (PMID 39996733, 2025). "Mechanistic study revealed that STM2457 augmented venetoclax activity by downregulating MCL1 and MYC, thereby increasing apoptosis in leukemia cells induced by venetoclax." (PMID 40169588, 2025). "Aberrant expression of MYC in leukemia results in an uncontrolled rate of proliferation and, thereby, a blockade of the differentiation process." (PMID 39940843, 2025). "Our study also highlights the crucial role of SETD1B-dependent H3K4me3 breadth in the MYC pathway in leukemia." (PMID 40341256, 2025). "FTO inhibitor 44/ZLD115 upregulates RARA and downregulates MyC in leukemia cells, inducing apoptosis." (PMID 39802639, 2025). "This inhibition works by limiting cholesterol synthesis and disrupting the distal regulation of leukemia stem cell‐specific MYC enhancer chromatin, thereby suppressing oncogenic AKT1 signaling and reducing MYC expression." (PMID 40145543, 2025).